PML (PML nuclear body scaffold)
Diseases named in the same sentence as PML in open-access papers (continued):
Sharing a sentence is not in itself a finding about the gene and the disease.
acute promyelocytic leukemia (continued). "The underlying mechanism(s) by which the PML::RARA fusion protein initiates acute promyelocytic leukemia is not yet clear." (PMID 38648485, 2024). "A unique subtype within AML is acute promyelocytic leukemia (APL) with PML::RARA, well-known among hematologists for its distinctive morphology, clinical features, and high cure rates with all-trans-retinoic acid (ATRA) combined with arsenic trioxide induction therapy." (PMID 39432585, 2024). "Recently, the interaction between dyslipidemia-related genes and hematologic malignancy genes has been reported; for instance, the PML/RARα fusion protein and peroxisome proliferator-activated receptor-α have a synergistic effect on acute promyelocytic leukemia." (PMID 37384286, 2023). "Acute promyelocytic leukemia (APL) is generated by the PML-RARA fusion gene." (PMID 37240786, 2023). "We therefore speculate that a SUMO ‘molecular glue’ mechanism might be enhancing centromere clustering, similar to what has been described for promyelocytic leukaemia nuclear bodies (PML-NBs)." (PMID 37970674, 2023). "Furthermore, arsenic trioxide targets PML-NBs very effectively in acute promyelocytic leukemia and we find that this agent is similarly effective against histone-mutated gliomas." (PMID 38066546, 2023). "A prominently studied disease is acute promyelocytic leukemia (APL), which is caused by the fusion genes PML-RARα and PLZF-RARα, which results in the atypical selection of corepressors suppressing the RA-targeted genes responsible for the terminal differentiation of promyelocytes." (PMID 37645246, 2023). "Furthermore, the ATO/ATRA drug combination which targets PML-NBs in acute promyelocytic leukemias has been shown to be effective in IDH-mutated AML, suggesting a possible PML involvement." (PMID 38066546, 2023). "PML‐retinoic acid receptor α (RARA) fusion proteins have dominant‐negative effects on PML body assembly and cause transcriptional repression of differentiation genes in acute promyelocytic leukemia (APL)." (PMID 36117111, 2022). "Additionally, in acute promyelocytic leukemia (PML), EVs contained high levels of PML retinoic acid receptor-α transcripts." (PMID 36106632, 2022). "Assays have been developed for three phenotypes of particular clinical significance: NPM1, Core Bind Factor (CBF)-AML (referring to the fusions gene RUNX1::RUNX1T1 and CBFB::MYH11) and Acute Promyelocytic Leukemia (APL) (referring to the fusion gene PML::RARA)." (PMID 35892893, 2022). "In this manuscript, we report torque teno mini virus (TTMV) as a cause of acute promyelocytic leukemia (APL) lacking PML::RARA in a 3-year-old boy." (PMID 36591487, 2022). "Interestingly, pathways related to mitochondrial functions and promyelocytic leukemia-nuclear bodies (PML-NB) were consistently modulated by NMN in both the acute and chronic regimen of Doxo." (PMID 36611902, 2022). "As pointed out by those investigators, the decrease in NEAT1 expression may be explained by the repression of NEAT1 by a transcriptional repressor as promyelocytic leukemia-retinoic acid receptor α (PML-RARα)." (PMID 33670447, 2021). "Promyelocytic leukemia with retinoic acid receptor alpha (PML-RARα)-fusion-mediated NEAT1 transcriptional repression might impair the myelopoiesis of acute promyelocytic leukemia cells." (PMID 34502451, 2021). "Our hypothesis is supported by previous studies that show that the loss of ELF4 causes a profound abrogation in BCR-ABL associated Chronic Myeloid Leukemia and the direct interaction between the Promyelocytic Leukemia (PML) gene and ELF4." (PMID 33836003, 2021). "Specifically, TRIB3 inhibits ubiquitylation and degradation of promyelocytic leukemia protein (PML) in acute promyelocytic leukemia progression by repressing proteasome recruitment and interaction with PML and by inhibiting the ubiquitin proteasome system activity." (PMID 33546420, 2021). "About 5–10% of AML patients have acute promyelocytic leukemia (APL) with PML-RARA fusion gene." (PMID 33335095, 2020).
acute promyelocytic leukemia (continued). "Scientific understanding of the AML biology has led to the development of targeted treatment approaches, i.e., the all-trans retinoic acid (ATRA) treatment for acute promyelocytic leukemia (APL) that carries the PML-RARα translocation or the use of FLT3 kinase inhibitors in FLT3-mutated cases." (PMID 32110991, 2020). "Thus, the top two AML genes, MPO (myeloperoxidase) and PML (promyelocytic leukemia) have the GCHs 22.96 and 21.95, below those of the 56th and the 59th ranked ribosomal proteins RPL29 (23.64) and RPL13 (22.12)." (PMID 31349573, 2019). "In acute promyelocytic leukemia, the achievement of PCR negativity for PML-RARα at the end of consolidation treatment is the most informative in terms of prediction of outcome and it is associated with a low risk of relapse and a high probability of long-term survival." (PMID 31067725, 2019). "The promyelocytic leukemia (PML) gene is located on the long arm of chromosome 15 and was first described as part of a recurrent chromosomal translocation found in more than 95% of patients diagnosed with acute promyelocytic leukemia (APL)." (PMID 31416160, 2019). "However, evidence suggests that TRIB3 contributes to acute promyelocytic leukemia progression by PML‐RARα stabilization via specific binding to SUMOylation motifs, thereby acting on PML‐RARα degradation and differentiation." (PMID 31254352, 2019). "It was also established that some fusion proteins found in hematopoietic malignancies, including p210BCR-ABL and PML-RARα which are drivers for chronic myeloid leukemia and acute promyelocytic leukemia, respectively, can be degraded through MA or other mechanisms." (PMID 31623164, 2019). "Using their favorite model, PML (promyelocytic leukaemia) bodies, they demonstrated how cells may use colloids for efficient storage and retrieval of vital information." (PMID 31405317, 2019). "Promyelocytic leukemia (PML) nuclear bodies (NBs) (also called ND10) are proteinaceous entities involved in the control of viral infection as part of the cell and nucleus-associated intrinsic antiviral response but also through innate immunity associated with the interferon (IFN) response." (PMID 30235352, 2018). "Promyelocytic leukemia (PML) proteins, which fuse with retinoic acid receptor alpha and induce tumors such as acute promyelocytic leukemia, were shown to be down-regulated by arsenic trioxide, and PML proteins are tightly involved in NLRP3 inflammasome activation." (PMID 30209319, 2018). "The role of retinoic acid receptor α (RARα) in hematopoiesis is very important, as the fusion of RARα gene with PML gene initiates acute promyelocytic leukemia where differentiation of the myeloid lineage is blocked, followed by an uncontrolled proliferation of leukemic blasts." (PMID 28635660, 2017). "It has been shown that the use of arsenic (As2O3) for therapeutic treatment of acute promyelocytic leukemia (APL) patients is effective because it triggers degradation of PML and oncogenic PML fusion proteins, such as PML-RARalpha, through promoting their hyper-SUMOylation." (PMID 28884683, 2017). "Because the zebrafish genome lacks a clear promyelocytic leukemia (PML) gene, it is impossible to assess the presence of ALT by probing for characteristic complexes of promyelocytic leukemia nuclear bodies associated with telomeres, known as APBs (ALT-associated PML bodies)." (PMID 27482813, 2016). "In this study we performed absolute quantification of the PML-RARA transcript by droplet digital polymerase chain reaction (ddPCR) in 76 newly diagnosed acute promyelocytic leukemia (APL) cases to verify the prognostic impact of the PML-RARA initial molecular burden." (PMID 25944686, 2015).
acute promyelocytic leukemia (continued). "We have previously shown that a specific promyelocytic leukemia-retinoic acid receptor alpha (PML-RARA) DNA vaccine combined with all-trans retinoic acid (ATRA) increases the number of long term survivors with enhanced immune responses in a mouse model of acute promyelocytic leukemia (APL)." (PMID 26378812, 2015). "Lack of MIXL1 expression in AML M3 acute promyelocytic leukemia, frequently associated with the PML-RARA translocation arising in the context of myeloid restricted gene expression program is also consistent with such a model." (PMID 25544748, 2014). "We also demonstrated that the knockdown of SET gene resulted in the upregulation of protein phosphatase 2 (PP2A) expression and the downregulation of promyelocytic leukemia and retinoic acid receptor α fusion gene (PML-RARα) expression, which were enhanced by As4S4 treatments." (PMID 24454695, 2014). "The tumor suppressor function of the promyelocytic leukemia (PML) protein was first identified as a result of its dysregulation in acute promyelocytic leukemia, however, its importance is now emerging far beyond hematological neoplasms, to an extensive range of malignancies, including solid tumors." (PMID 23730625, 2013). "Since its discovery, 25 years ago, promyelocytic leukemia (PML) has been an enigma." (PMID 23847762, 2013). "Interestingly, FOXL2 SUMOylation promotes its transient recruitment to subnuclear structures that we demonstrate to be PML (Promyelocytic Leukemia) Nuclear Bodies." (PMID 22022399, 2011). "Promyelocytic leukemia nuclear bodies (PML NBs) are involved in the regulation of apoptosis, antiviral responses, the DNA damage response and chromatin structure, but their precise biochemical function in these nuclear pathways is unknown." (PMID 20205709, 2010). "Interestingly, ATO inhibits the interaction of the corepressor SMRT with the fusion protein promyelocytic leukemia-retinoic acid receptor-a (PML-RARa) contributing to possible mechanisms in iAs-mediated remission in acute promyelocytic leukemia (APL)." (PMID 19707557, 2009). "TRIM19/PML, besides its involvement in acute promyelocytic leukemia, has been shown to interfere with the replicative cycle of many DNA and RNA viruses and evidence indicate that it may represent a broad-spectrum cellular defence factor." (PMID 18673550, 2008). "The PML gene encodes a Zn-binding protein in the tripartite motif (TRIM) family and is often involved in the translocation with the retinoic acid receptor-α gene associated with acute promyelocytic leukemia." (PMID 16330358, 2005). "Acute promyelocytic leukemia (APL) is a distinct subtype of acute myeloid leukemia characterized by the PML-RARA fusion gene and frequent coagulopathy." (PMID 41970134, 2026). "Acute promyelocytic leukemia (APL) is a subtype of acute myeloid leukemia characterized by the presence of the promyelocytic leukemia-retinoic acid receptor alpha (PML::RARA) fusion gene." (PMID 42131682, 2026). "Among leukemia subtypes, acute promyelocytic leukemia (APL) is a variant of acute myeloid leukemia (AML) and is typically caused by a translocation between chromosomes 15 and 17, resulting in the PML-RARα gene fusion." (PMID 40277545, 2025). "To address this issue, we developed an efficient approach to estimate the similarity between leukemic blasts and normal blood cells in BMMCs, taking a patient with PML::RARA AML [also known as acute promyelocytic leukemia (APL)] as an example." (PMID 39945785, 2025). "Authors finally evaluated the impact of Zharp1-211 on the GVL effect in B6 recipients receiving acute promyelocytic leukemia (APL) cells, which are driven by the PML-RARA fusion gene and recapitulate the human disease." (PMID 40007541, 2025). "Acute promyelocytic leukemia (APL) is classically driven by the PML-RARA fusion oncogene and characterized by a maturation arrest of myeloid precursors." (PMID 40951356, 2025).
acute promyelocytic leukemia (continued). "Furthermore, in response to DNA damage, IKKε undergoes robust SUMOylation at Lys231 by the cellular SUMO E3 ligase TOPORS, resulting in IKKε nuclear translocation, particularly within Promyelocytic leukemia (PML) nuclear bodies (PML NBs), and activation of the anti-apoptotic function of NF-κB." (PMID 39823515, 2025). "The combination of ATRA and ATO degrades the PML-RARα fusion protein that drives acute promyelocytic leukemia (APL), leading to cell cycle arrest and cell death with minimal toxicity." (PMID 41292878, 2025). "The PML/RARA fusion gene, a characteristic hallmark of acute promyelocytic leukemia (APL), was detected in three patients with acute myeloid leukemia type M3 (AML-M3)." (PMID 40028267, 2025). "The molecular basis of arsenic’s success in treating acute promyelocytic leukemia (APL) lies in rescuing PML NBs." (PMID 39551864, 2024). "The re-assembly of PML NBs might lead to an ~100% cure of acute promyelocytic leukemia." (PMID 39587079, 2024). "In acute promyelocytic leukemia (APL), the fusion protein PML/RARα downregulates the expression of CDKN2D by suppressing its promoter activity, which in turn affects leukemia cell proliferation and differentiation." (PMID 39422621, 2024). "In 2022, A study demonstrated that PML/RARα fusion proteins that drive chromosomal translocation production in acute promyelocytic leukemia (APL) are assembled by LLPS into nucleosomal structures." (PMID 38347544, 2024). "All-trans retinoic acid (ATRA) is a well-established treatment for acute promyelocytic leukemia (APL), which is induced by the fusion protein PML::RARA." (PMID 39499902, 2024). "Acute promyelocytic leukemia (APL) is initiated by the PML::RARA fusion gene in greater than 95% of cases." (PMID 38648485, 2024). "The driver oncogenic fusion protein (PML/RARα) of acute promyelocytic leukemia (APL) is a key factor in initiating APL leukemogenesis." (PMID 39000393, 2024). "We also discuss how altered condensate formation contributes to malignant transformation of hematopoietic cells, as described for promyelocytic leukemia protein (PML) in PML::RARA-driven acute promyelocytic leukemia (APL) and other myeloid malignancies." (PMID 37388925, 2023). "Acute promyelocytic leukemia (APL) is a distinct sub-type of acute leukemia defined by the presence of the 15;17 translocation, resulting in the formation of the PML-RARA fusion protein, which blocks differentiation at the promyelocyte stage." (PMID 37835461, 2023). "Examples include tyrosine kinase inhibitors (TKI) in chronic myelogenous leukemia (CML) that block BCR::ABL1 kinase activity and differentiation therapy with all-trans retinoic acid (ATRA) in acute promyelocytic leukemia (APL) targeting the (PML::RARA) fusion." (PMID 37699001, 2023). "Acute promyelocytic leukemia (APL) is an aggressive subtype of acute myeloid leukemia (AML) in which the PML/RARα fusion protein exerts oncogenic activities by recruiting repressive complexes to the promoter of specific target genes." (PMID 36536122, 2023). "Of note, degradation of PML/RARalpha oncoprotein by arsenic trioxide enables acute promyelocytic leukemia (APL) a curable leukemia, because arsenic trioxide can eradicate APL leukemic stem cells by degradation of the oncoprotein." (PMID 37664023, 2023). "Acute promyelocytic leukemia (APL) with a PML-RARα fusion oncogene is so far the only AML subgroup where such targeted agents can be used successfully without concomitant chemotherapy." (PMID 37987319, 2023). "In acute promyelocytic leukemia (APL) with PML::RARα translocations and acute myeloid leukemia with KMT2A::MLLT3 (MLL::AF9) fusions, f-circRNAs can be oncogenic or sustain the oncogenic properties of chimeric proteins." (PMID 36585787, 2023).
acute promyelocytic leukemia (continued). "We used the TransCRISTI gene knock-in method to insert a PML coding sequence in front of the PML native promoter to present a therapeutic model approach for the acute promyelocytic leukemia (APL) disease, in which a translocation results in PML gene knockout." (PMID 35232993, 2022). "The oncofusion protein PML-RARα which drives acute promyelocytic leukemia (APL) directly suppresses p18INK4c expression which is downregulated in APL blasts compared to normal promyelocytes." (PMID 36033505, 2022). "Altered signaling pathway due to the chromosomal rearrangement event of PML–RARA fusion is often observed only in acute promyelocytic leukemia (APL), a distinct subgroup of acute myeloid leukemia (AML)." (PMID 36173247, 2022). "Promyelocytic leukemia (PML) proteins are involved in the pathogenesis of acute promyelocytic leukemia (APL)." (PMID 35594310, 2022). "Similarly, the promyelocytic leukemia-retinoic acid receptor α (PML/RARα) has two primary NLS, which include one from the PML (159RNKKKK164), and the other from the RARα (486RKVIK490), the NLS of the RARα portion in NLS-RARα is more favorable for the nuclear localization of NLS-RARα." (PMID 34022911, 2021). "The PML gene was first discovered in an acute promyelocytic leukemia (APL) as part of PML-RARα fusion oncoprotein." (PMID 33807177, 2021). "Acute promyelocytic leukemia (APL) is a subset of acute myeloid leukemia (AML) which is characterized by the fusion of promyelocytic leukemia PML and retinoic acid receptor- alpha (RAR-alpha) genes." (PMID 34140003, 2021). "In UPN01, the diagnosis of acute promyelocytic leukemia [APL with t (q22;q21); PML–RARA fusion (bcr3)] was established." (PMID 34950586, 2021). "Acute promyelocytic leukemia, which is classified as AML M3, is characterized by a translocation that leads to the creation of a fusion between the PML and RARA (retinoic acid receptor) genes." (PMID 34575830, 2021). "For instance, it was found that acute promyelocytic leukemia (APL), which contains the chromosomal translocation PML/RARα, can evade immune control by suppressing the PU.1-dependent activation of immunosubunits." (PMID 34206607, 2021). "Promyelocytic leukemia (PML)–retinoic acid receptor alpha (RARα) is a fusion RNA found in almost 95% of acute promyelocytic leukemia (APL)." (PMID 33557176, 2021). "It is demonstrated that USP18 stabilizes PML/RARα protein and inhibits cell apoptosis in all-trans-retinoic acid (RA)-sensitive and RA-resistant acute promyelocytic leukemia (APL) cells." (PMID 34454635, 2021). "Mechanistically, PCID2 physically associated with Promyelocytic leukemia protein (PML), the gene has been demonstrated to be involved in the development of acute promyelocytic leukemia (APL)." (PMID 34625711, 2021). "A recent study has shown that HOTAIRM1 can enhance autophagosome formation to degrade oncoprotein PML–RARA by sponging miR-20a to upregulate ULK1 in acute promyelocytic leukemia (APL)-ascites mouse model and APL cell lines." (PMID 33050642, 2020). "Acute promyelocytic leukemia (APL) is a hematological disease characterized by a balanced reciprocal translocation that leads to the synthesis of the oncogenic fusion protein PML-RARα." (PMID 33167477, 2020). "PML/RARα-positive blasts from acute promyelocytic leukemia (APL) patients display lower levels of miRNA let-7c than in regular promyelocytes." (PMID 33519805, 2020). "PHRF1 (PHD and RING finger domain-containing protein 1) suppresses acute promyelocytic leukemia (APL) by promoting TGIF (TG-interacting factor) ubiquitination, while the PML-RARα protein interferes with PHRF1-mediated TGIF breakdown to facilitate APL." (PMID 32730336, 2020). "Notably, the EBV tegument protein BNRF1 targets ATRX and DAXX for sequestration in promyelocytic leukemia (PML) bodies at this time point, suggesting that HIRA and newly induced CAF1 may be responsible." (PMID 33109754, 2020).